SGSM3 (small G protein signaling modulator 3)
Description:
GTPase-activating protein (GAP) specific for Rab5 small GTPase for which it accelerates the intrinsic GTP hydrolysis rate, thereby controlling trafficking through the early endocytic pathway. May play a cooperative role in NF2-mediated growth suppression of cells.
Synonyms: RabGAPLP; MAP; RUTBC3; DJ1042K10.2; RUSC3; RabGAP-5; RABGAP5; CIP85; MRT84
Tractability: PROTAC: ubiquitination databases record sites on it; its protein half-life has been measured.
Gene: Protein-coding gene on chromosome 22 (40,370,564 to 40,410,289, forward strand). Ensembl gene ENSG00000100359.
Subcellular location: Cytoplasm
Subcellular location (Human Protein Atlas): Golgi apparatus
Gene Ontology:
Molecular function: GTPase activator activity; protein binding; small GTPase binding
Biological process: endosomal transport; plasma membrane to endosome transport; positive regulation of GTPase activity; Rap protein signal transduction; regulation of cilium assembly; regulation of endocytosis; regulation of Rab protein signal transduction; positive regulation of protein catabolic process
Cellular component: cytoplasm; cytosol; Golgi apparatus; gap junction
Genetic constraint (gnomAD): Loss-of-function variants: 94 observed, 94.93 expected, observed/expected ratio (o/e) 0.99, 90% interval 0.84 to 1.17. The upper end of that interval is the gene's LOEUF score, 1.17, which puts it in group 5 of 6, group 1 being the genes least tolerant of losing a copy. Missense variants: 1,000 observed, 996.86 expected, observed/expected ratio (o/e) 1, 90% interval 0.95 to 1.06. Synonymous variants: 483 observed, 420.71 expected, observed/expected ratio (o/e) 1.15, 90% interval 1.07 to 1.24.
Homologues: Orthologues: chimpanzee SGSM3 (99% identical), macaque SGSM3 (96% identical), mouse Sgsm3 (94% identical), dog SGSM3 (93% identical), rabbit SGSM3 (93% identical), guinea pig SGSM3 (93% identical), rat Sgsm3 (91% identical), pig SGSM3 (90% identical), tropical clawed frog sgsm3 (85% identical), zebrafish sgsm3 (79% identical), Drosophila melanogaster CG12241 (65% identical), Caenorhabditis elegans tbc-18 (45% identical). Paralogues in human: TBC1D9 (25% identical), TBC1D9B (25% identical), TBC1D8B (23% identical), TBC1D8 (22% identical), TBC1D2 (14% identical), TBC1D2B (14% identical), TBCK (13% identical), TBC1D1 (12% identical), RABGAP1 (12% identical), TBC1D10A (12% identical), TBC1D10B (12% identical), TBC1D4 (12% identical), and 33 more.
Diseases named in the same sentence as SGSM3 in open-access papers:
SGSM3 is named in the same sentence as 12 diseases in open-access papers, as found by Europe PMC text mining. Sharing a sentence is not in itself a finding about the gene and the disease. The quoted sentences say what the papers report.
breast carcinoma (4 papers, 2015 to 2024). "It should be noted that a polymorphism (rs17001868) found in the SGSM3 gene has been associated with mammographic dense areas of the breast, which represents a factor of breast cancer risk." (PMID 29108258, 2017). "The ZNF365, ESR1, LSP1 and SGSM3 loci are also associated with breast cancer risk, implicating a shared genetic basis of mammographic density and breast cancer." (PMID 26275715, 2015). "The only information in the literature associating this protein with breast cancer described a decrease of SGSM3 mRNA in breast cancer tissue compared to normal tissue, which is in contrast with the significant increase of expression in LCLs of BRCAX affected individuals observed in our study." (PMID 29108258, 2017). "Interestingly, three genes in our list (ZNF365, SGSM3, and LSP1) were significantly annotated (using Webgestalt and Disgenet) with the “category mammographic density”, that is a strong risk factor for breast cancer." (PMID 28569218, 2017).
hepatocellular carcinoma (2 papers, 2017 to 2025). A malignant tumor that arises from hepatocytes. "SGSM3 has also been associated with hepatocellular carcinoma." (PMID 29108258, 2017). "Small G protein signaling modulator 3 (SGSM3) participates in the signaling pathway of small G protein‐coupled receptors, influencing susceptibility to hepatocellular carcinoma." (PMID 41409896, 2025).
bladder cancers (1 paper, 2020). "On the other hand, several studies have shown that SGSM3 is associated with the risk of some cancers, including liver, breast, colorectal and bladder cancers." (PMID 32271805, 2020).
Intellectual disability (1 paper, 2025). "SGSM3 loss‐of‐function cause nonsyndromic intellectual disability phenotype." (PMID 39390489, 2025).
myocardial infarction (1 paper, 2020). Gross necrosis of the myocardium, as a result of interruption of the blood supply to the area, as in coronary thrombosis. "In our previous study, we found that small G protein signaling modulator 3 (SGSM3), a partner of Cx43, contributes to myocardial infarction (MI) in rat hearts." (PMID 32271805, 2020).
tumor (2 papers, 2019 to 2023). "We further investigated SGSM2 and SGSM3 mRNA levels in tumours and paired normal tissues from 53 BC patients via RT-PCR." (PMID 30744493, 2019). "However, SGSM3 was homogenously expressed in both tumour and normal tissues." (PMID 30744493, 2019). "Compared with SGSM3 expression, SGSM2 expression in tumours was significantly higher, and its percentage of occurrence in the T > N group was 74%." (PMID 30744493, 2019). "According to our first screening, SGSM1 mRNA was not expressed in BC or breast epithelial cells, and compared with SGSM2 expression, SGSM3 expression was not different between normal breast tissue and tumour tissues based on RT-PCR." (PMID 30744493, 2019).
SGSM3 also shares sentences with these, for which no sentence is quoted: Arrhythmia (2 papers); cancer (2); autism (1); depression (1); infection (1); skin cutaneous melanoma (1).